ALB (albumin)
Diseases named in the same sentence as ALB in open-access papers (continued):
Sharing a sentence is not in itself a finding about the gene and the disease.
malnutrition (continued). "Besides, a reduced serum albumin level is a recognized clinical sign of malnutrition, and malnutrition causes respiratory muscle weakness and reduces pulmonary function." (PMID 36262258, 2022). "This may be of importance since lowered albumin levels have been independently associated with both malnutrition and inflammation." (PMID 36432461, 2022). "Measuring albumin upon admission of patients with COVID-19 would help to identify patients with a higher risk of malnutrition, and support measures could be adapted to the patients, improving the prognosis." (PMID 36558522, 2022). "However, in their study, patients with severe malnutrition (weight loss over 10%, albumin < 30 g/L or BMI < 18.5 kg/m2) were excluded." (PMID 36505253, 2022). "Thirdly, low albumin levels are caused by hemodilution, chronic inflammatory states, hepatic congestion, malnutrition, cachexia due to volume overload, and proteinuria or intestinal disease, there is a deficiency in this study because of the limitation of the database." (PMID 36171266, 2022). "Overall, 26.9% of patients had a high MCV, which was significantly associated with male sex, habitual smoking and drinking, multiple primary malignancies, and malnutrition, as estimated by the body mass index, hemoglobin and serum albumin values, and the Geriatric Nutritional Risk Index." (PMID 37601605, 2022). "A low level of serum albumin may reflect malnutrition, which has previously also been shown to be associated with depression and poor clinical outcomes in dialysis patients." (PMID 36612797, 2022). "In addition to NCDs, we note protein malnutrition in people over 70 years of age, weight loss and body mass index and albumin levels below the recommended threshold, indicating malnutrition." (PMID 35821858, 2022). "Changes in α-HBDH levels and these markers may affect mutually, such as reduced albumin level indicates malnutrition and lower LVEF is associated with damage of systolic function of myocardium." (PMID 36204589, 2022). "Patients admitted for acute diverticulitis, an acute inflammatory state, may have falsely low levels of albumin, thereby resulting in a misdiagnosis of malnutrition, causing possible overestimation of nutritional deficiency in this patient population." (PMID 35989747, 2022). "The results showed that gender (OR = 2.371), age (OR = 3.646), weight loss (OR = 11.945), reduced food intake (OR = 27.888), serum albumin expression (OR = 2.936) were risk factors for malnutrition in patients with CKD, and the difference was statistically significant (P < 0.05)." (PMID 36687720, 2022). "Moreover, the MNA long-form had a strong agreement with serum albumin concentration, for identifying elderly individuals with malnutrition or those at risk of malnutrition (weighted kappa = 0.556 (0.470, 0.642)." (PMID 36411835, 2022). "As a manifestation of malnutrition, poor survival is associated with low serum albumin levels." (PMID 36569222, 2022). "Increased inflammation linked to vascular permeability results in albumin leakage to the extravascular space; coupled with malnutrition, it may lead to hypoalbuminaemia." (PMID 35407640, 2022). "Furthermore, malnutrition was an independent risk factor of sarcopenia, as lower albumin/prealbumin levels and higher malnutrition-inflammation score (MIS) were observed in sarcopenic groups vs. non-sarcopenic." (PMID 34383112, 2022). "Low albumin, a marker of malnutrition and severe sepsis, may be associated with mortality, and the relevance of hypocalcemia in patients with inflammation is still being debated." (PMID 35743797, 2022). "The initial value of serum albumin might also be a result of malnutrition or an underlying disease that can worsen the nutritional status of the patient." (PMID 36412638, 2022). "In our case, although we did not suspect occult infection, hypoalbuminemia may have been caused by not only malnutrition, but by albumin‐synthetic depression upon liver dysfunction." (PMID 38868660, 2022).
malnutrition (continued). "Serum pre-albumin levels of less than 10 mg/dL are associated with malnutrition." (PMID 35892736, 2022). "GNRI is an integration of serum albumin and body mass index (BMI); therefore, this constitutive relation may explain the association between malnutrition in stroke patients and increased mortality." (PMID 36432473, 2022). "In addition, patients with OSCC are susceptible to malnutrition 50 and food intake dysfunction 51 and therefore have a decreased serum albumin level." (PMID 36046647, 2022). "Additionally, serum albumin level is a biochemical marker of nutritional status and is strongly associated with malnutrition severity, which is regarded as a general risk factor in critically ill patients." (PMID 36579497, 2022). "Malnutrition in patients is accompanied by low levels of lymphocytes, prealbumin, and albumin, which are significantly associated with a higher risk of transfer to intensive care unit (ICU), a declined immune response and increased risk of infections, prolonged hospitalization, and poor prognosis." (PMID 36558436, 2022). "While hypoalbuminemia is often used to diagnose malnutrition, albumin may be low due to alternate causes in response to an acute inflammatory state, as a result of increased vascular permeability and resultant shifting of albumin to the extravascular space." (PMID 35989747, 2022). "Serum albumin is the most abundant protein in human blood plasma, and several factors may influence the serum albumin concentration; among these factors, malnutrition and inflammation may be the main cause of reduced serum albumin levels." (PMID 36286310, 2022). "Using serum albumin level as a marker of chronic malnourishment, it has been found that, after adjusting for RACHS-1 risk categories, a higher albumin level was associated with a decrease in B-type natriuretic peptide (BNP), and an overall trend toward decreased duration of dopamine requirement." (PMID 35433875, 2022). "Serum albumin levels may also be associated with infection, dehydration, and nutritional deficiency." (PMID 36011757, 2022). "Low serum albumin levels can be used as a marker for nutritional deficiency." (PMID 36589182, 2022). "Serum albumin is related to infection, dehydration, and nutritional deficiency." (PMID 35602847, 2022). "Low levels of albumin are related to malnutrition and both have been associated with anxiety." (PMID 34831713, 2021). "Low albumin level might be caused by liver failure or malnutrition/malapsorption, and is often observed during inflammatory response." (PMID 34730889, 2021). "A low albumin level is also associated with malnutrition or malabsorption, thus the higher levels of serum globulins generated by the accumulation of immunoglobulins and acute phase proteins are a better indicator of a more severe degree of inflammatory response." (PMID 34206598, 2021). "PONS is a modified version of the malnutrition universal screening tool and determines the presence of nutrition risk based on BMI, recent body weight loss, decrement of dietary intake, and preoperative albumin concentration." (PMID 34235132, 2021). "However, the clinical impact of albumin removal due to PPL differs from that of albumin deficiency as malnutrition." (PMID 34336874, 2021). "Hypotheses for decreased albumin concentration in cancer patients were varied, including malnutrition, increased albumin consumption due to the expression of cancer cells, and inhibition of albumin synthesis caused by systemic inflammation." (PMID 34041866, 2021). "The association between serum albumin and anemia may be due to a reduction in hepatic protein synthesis as a result of decreased food intake, malnutrition, advanced age, or sarcopenia." (PMID 34873402, 2021). "A low serum albumin concentration is associated with malnutrition and weight loss." (PMID 34645392, 2021).
malnutrition (continued). "According to available data from the five studies, patients with lower LDL-C also had lower plasma albumin and total cholesterol concentrations, which may reflect underlying malnutrition status." (PMID 33874960, 2021). "Decreases in serum albumin before PD initiation or during PD may cause malnutrition and poor health conditions in the long term and increase the risk of peritonitis." (PMID 34337034, 2021). "It is well known that low albumin is often associated with malnutrition." (PMID 34355041, 2021). "Previously, albumin was detected to be a predictor of treatment failure in PDAP, partly because of malnutrition; the albumin level was associated with technique failure in the univariate analysis in this study, but not a predictor in the multivariate logistic regression analysis." (PMID 33842502, 2021). "Albumin, pre-albumin, and hemoglobin have been widely used as representative markers of nutritional status, and lower serum albumin, pre-albumin, and hemoglobin levels are also known to be associated with malnutrition and impairment of ADL." (PMID 33529213, 2021). "Despite the fact that hypoalbuminemia is frequently considered an important biochemical marker of nutritional status because of its association with malnutrition, albumin lacks specificity as it may decrease as a consequence of other comorbidities." (PMID 33924581, 2021). "When combined, elevated acute inflammation and decreased serum albumin may indicate nutritional deficiency, sarcopenia, and poor patient performance, which could all influence the prognosis of HNC." (PMID 33652976, 2021). "In contrast, accumulation of advanced glycation end products, a biomarker of oxidative stress measured using skin auto fluorescence, was significantly associated with markers of malnutrition in HD patients such as lower serum albumin, lower handgrip strength, and lower protein intake." (PMID 33076282, 2020). "Interestingly, though our patients had higher malnutrition risk, they were younger and had higher albumin levels than the others." (PMID 33348880, 2020). "Traditionally, the concept of malnutrition in CKD dialysis patients usually refers to nutritional abnormality caused by insufficient dietary protein intake or excessive loss of albumin that was once referred to as ‘malnutrition inflammation complex syndrome’ or ‘uremic malnutrition’." (PMID 32490516, 2020). "In a review of 44 studies involving 26,281 patients, the prevalence of malnutrition was approximately 45.7% when different criteria such as body mass index (BMI), weight loss, or albumin concentration were considered; however, it was approximately 18.7% using the MNA." (PMID 33266264, 2020). "The score was proposed in order to increase sensitivity in the identification of patients at risk of malnutrition and was defined retrospectively as any of albumin <2.8 g/dl, weight loss >10% from pre-transplant baseline, BMI <25th percentile or <5th percentile (Score NUT25 and NUT5 respectively)." (PMID 33488571, 2020). "Systemic inflammation followed by a decrease in serum albumin levels may lead to sarcopenia, nutritional deficiency, and subsequent poor performance." (PMID 32587804, 2020). "Furthermore, the serum albumin level reflects the nutritional status, and elderly patients with underlying malignant condition are at risk of malnutrition." (PMID 31660937, 2019). "Malnutrition (low albumin) before surgery was associated with 30-day mortality." (PMID 31827617, 2019). "In addition, a low albumin level is an indicator of malnutrition and has been associated with higher mortality in cancer and ACS." (PMID 31096693, 2019). "Elevated CRP-levels are associated with various inflammatory processes, whereas decreased serum albumin levels are associated with chronic diseases and malnutrition and therefore can be a result of chronic inflammatory processes that are known to play a central role in carcinogenesis." (PMID 31788452, 2019).
malnutrition (continued). "It has been reported that lower Mg levels are associated with reduced serum phosphorus, calcium, and albumin levels; thus, they might be indicative of malnutrition." (PMID 30977017, 2019). "Conditions associated with “low” levels of albumin are as follows: ascites, burns, glomerulonephritis, liver disease (hepatitis or cirrhosis), malabsorption syndrome (e.g., Crohn's disease, celiac disease, or Whipple disease), and malnutrition." (PMID 31662844, 2019). "The association between FID and malnutrition verified by the observation of lower BMI, albumin, transferrin, waist circumference, and mid-upper arm circumference in this group seemed to indicate that protein-energy malnutrition might have been a factor." (PMID 31441929, 2019). "Low serum albumin may reflect increased catabolism caused by inflammation, reduced production owing to malnutrition, and urinary albumin loss in proteinuric kidney disease." (PMID 31057617, 2019). "On the other hand, it has been reported that vitamin D deficiency may be associated with increased MPV, whereas malnutrition, lower values of albumin, creatinine, protein intake, and haemoglobin were associated with a higher P count." (PMID 31827693, 2019). "Besides the risk screening tools named above, blood markers for malnutrition like albumin, total leucocyte count and transferrin are in controversial discussion." (PMID 29544497, 2018). "Therefore, higher levels of C-reactive protein generally suggest an acute infectious or inflammatory process, whereas low albumin is more frequently associated with chronic diseases and is often associated with nutritional deficiency." (PMID 29267535, 2018). "Previous studies using BMI, body weight or serum albumin as markers to evaluate nutritional status have indicated that malnutrition could cause elevated mortality during treatment in patients with TB." (PMID 28085951, 2017). "When studies on patients with acute disease were also included, the estimated concentrations of albumin and prealbumin were decreased by more than 5% for groups with malnutrition risk as assessed by NRS-2002 and SGA respectively, although those by MNA were relatively stable." (PMID 28771192, 2017). "It is generally considered that chronic and progressive malnutrition during AN is associated with an adaptative decrease of whole body protein breakdown, which may also include a reduction of albumin degradation." (PMID 28257095, 2017). "Together this suggests that low albumin levels in cancer patients may cause a high mortality rate not only by malnutrition but also via augmented malignant tumor phenotypes and inefficient drug delivery." (PMID 28417928, 2017). "Hypoalbuminemia, defined as a serum albumin level < 2.1 mg/dL, is a common surrogate marker of malnutrition and is independently associated with greater postoperative complications, such as surgical site infections (SSI) and postoperative morbidity and mortality." (PMID 28272344, 2017). "Low level of plasma albumin is associated with cachexia, a malnutrition status." (PMID 28417928, 2017). "A low albumin level is associated with malnutrition and low animal protein intake." (PMID 28360943, 2017). "Low serum albumin levels are associated with aging and medical conditions such as cancer, liver dysfunction, inflammation, and malnutrition and might be an independent predictor of long-term mortality in healthy older populations." (PMID 27276092, 2016). "However, the mortality risks associated with serum albumin were not only a consequence of malnutrition, but also inflammation." (PMID 27780214, 2016). "Moreover, 20 % of all our patients had albumin levels <30 g/dl and 31 % hemoglobin levels <10 g/dl, suggesting that our population is predisposed to malnutrition and anemia." (PMID 27473376, 2016).
malnutrition (continued). "Following the MNA criteria, 98% of the malnourished patients had low albumin level(n=40), and the percentage with normal levels grew according to the improvement of thenutritional level: malnourished 2%, in risk of malnutrition 13% and out of risk formalnutrition 21%." (PMID 27508908, 2016). "Thus, serum albumin cannot always be associated with malnutrition in patients under HD, although hypoalbuminemia is a risk for mortality in those patients." (PMID 27870908, 2016). "Regarding the first sample for albuminemia tests, the results showed an statisticallysignificant difference from MNA with serum albumin profile (p=0,000) and following thepost-hoc Tukey test, there is a difference between the malnourished group and those outof risk of malnutrition (p=0,000)." (PMID 27508908, 2016). "Serum albumin levels thus seem to reflect both systemic inflammation (and nutritional deficiency), as well as synthetic liver function and may even have a role in protection against HCC growth." (PMID 28580457, 2016). "Similarly, an index of nutritional deficiency including low BMI, low albumin, and low cholesterol has been associated with approximately 2-fold higher rate of RCC-specific death." (PMID 26506437, 2015). "Moreover, each 10-fold increase in BCL was associated with a 2.64-fold increase in the probability of malnutrition development (serum albumin levels <3.6 g/dL) in these subjects." (PMID 24428882, 2014). "Albumin levels are associated with cachexia and ascites, leading to malnutrition in ROC patients." (PMID 25298213, 2014). "In primary care, a low calcium concentration may be due to vitamin D deficiency, malnutrition, kidney and intestinal disease, or a malignancy-dependent low albumin concentration." (PMID 24299047, 2013). "A low albumin may be associated with mortality both as a marker of malnutrition and, along with elevated alkaline phosphatase, severe sepsis." (PMID 22276145, 2012). "Decreased serum albumin is the main diagnostic indicator of malnutrition in patients with AKI." (PMID 20346168, 2010). "Liver disease may interfere with biomarkers of malnutrition such as albumin, making it difficult to identify subjects at risk of malnutrition and to evaluate the need for nutritional intervention." (PMID 21234351, 2010). "RBP (plasma half-life: 12 h), TRF (half-life: 8 days) and albumin (half-life: 15 days) have been selected as nutritional deficiency indicators included in the Nutritional Risk Index, being representative, respectively, of proteins with very short, short, and long to extremely long half-lives." (PMID 20840337, 2010). "The Nutrition Risk Index uses body weight and serum albumin to calculate a malnutrition score." (PMID 16952310, 2006). "Furthermore, albumin showed exploratory performance in ROC analyses for malnutrition and vitamin D deficiency (AUCROC 0.814 and 0.725, respectively), which should be interpreted cautiously given potential overlap with MNA-defined nutritional status and the limited sample size." (PMID 41978110, 2026). "However, some evidence suggests that serum albumin measurement may still serve as a valuable diagnostic tool for assessing malnutrition, particularly in patients undergoing cardiac transplantation and orthopedic procedures." (PMID 40161084, 2025). "Although the medians in the groups with malnutrition risk and normal nutritional status were at a similar level, based on the spread of values, it can be concluded that the number of subjects with higher albumin levels was higher in the group with adequate nutritional status." (PMID 40094974, 2025). "In patients with diabetic CKD stage 5 (DMCKD5), lower PA (< 4.17°), which represents malnutrition status, was significantly associated with lower eGFR, lean tissue indices, and albumin levels, suggesting that PA could be used as a marker to reflect nutritional status in patients with DMCKD5." (PMID 40170053, 2025).